PADI2 (peptidyl arginine deiminase 2)
Diseases named in the same sentence as PADI2 in open-access papers (continued):
Sharing a sentence is not in itself a finding about the gene and the disease.
COVID-19 (3 papers, 2022 to 2024). A disease caused by infection with severe acute respiratory syndrome coronavirus 2. "Carriers of the rs1005753 G/G genotype in the PADI2 gene presented susceptibility for severe COVID-19, while the heterozygous carriers in rs11203366, rs11203367, and rs874881 of the PADI4 gene showed risk of death." (PMID 38524554, 2024). "The association analysis of individual SNPs indicated that the genotype related to susceptibility to severe COVID-19 was PADI2 rs1005753 G/G (OR = 1.69, p = 0.045)." (PMID 38524554, 2024). "Here, the rs1005753 in PADI2 was individually associated with inflammation and severe COVID-19, whereas rs2235926 was a protective marker for inflammation and death by COVID-19." (PMID 38524554, 2024). "CD274 (PD-L1), which has been implicated in dysregulated neutrophil responses in severe COVID-19, and PADI2, an enzyme involved in the citrullination of arginine residues and neutrophil extracellular trap (NET) formation, were also highly expressed in the TV group compared to the other two groups." (PMID 37026002, 2023). "For this reason, we length of stay performed the first candidate gene study evaluating the association of SNPs in PADI2 and PADI4 with inflammation markers, severity, and death by COVID-19." (PMID 38524554, 2024). "The main findings in our study were that: 1) SNPs rs1005753 of PADI2 and rs874881, rs11203367, and rs11203366 of the PADI4 gene are associated with susceptibility to severe COVID-19 and death." (PMID 38524554, 2024). "Our results suggest that the haplotypic combination of GTACC and some individual genotypes of PADI2 and PADI4 contribute to the subjects' susceptibility for severity and death by COVID-19." (PMID 38524554, 2024). "SNPs in the PADI2 and PADI4 genes associated with susceptibility to severe COVID-19 and death showed a more robust association if combined as haplotypes." (PMID 38524554, 2024). "However, our results provide some perspectives on the influence of PADI2 and PADI4 gene variants on clinical and biochemical COVID-19 outcomes." (PMID 38524554, 2024). "The association of single SNPs and PADI2 and PADI4 haplotypes with abnormal markers of inflammation, COVID-19 severity and death might be explained by the higher expression and activity of PAD2 and PAD4 enzymes in monocytes and neutrophils." (PMID 38524554, 2024). "In conclusion, individual SNPs in PADI2 and PADI4 were related to COVID-19 severity and death risk." (PMID 38524554, 2024). "Therefore, this study aims to analyze the individual association of SNPs and haplotypic combination in PADI2 and PADI4 with inflammation markers, severity, and death by COVID-19 in a Mexican population." (PMID 38524554, 2024). "However, genes related to distinct mechanisms of NET induction were differentially expressed in the COVID-19(+) TV and COVID-19(-) PU control groups, with COVID-19(+) TV samples expressing PADI2 versus PADI4 expression in COVID-19(-) PU controls." (PMID 37026002, 2023). "However, the haplotypic combination GTACC between SNPs of PADI2 [rs1005753, rs2235926] and PADI4 [rs11203366, rs11203367 and rs874881] was associated with susceptibility for severe COVID-19 (OR = 1.59, p = 0.007), as well as with susceptibility to present a PLR index ≥303 (OR = 1.93, p < 0.001)." (PMID 38524554, 2024). "Our results also suggest that SNPs in PADI2 and PADI4 play a synergistic role as modifiers of enzymes expression or activity, contributing to the clinical manifestation and outcomes of COVID-19 due to its role in NETosis, cytokine citrullination, platelet activation, and thrombosis." (PMID 38524554, 2024). "•The combination of PADI2 and PADI4 SNPs exhibits a synergistic role in the COVID-19 severity." (PMID 38524554, 2024).
COVID-19 (continued). "In comparison to the COVID-19(-) PU controls, genes highly expressed in the TV group fell into categories that included neutrophil dysfunction (CD274, PADI2), inhibition of B and T cell responses (CD22, IRF4, ORAI1), and upregulation of pro-inflammatory response pathways (CARD8, MAPK7, IRF7, IFIH1)." (PMID 37026002, 2023). "Similarly, SNPs in PADI2 are related to the level of antibodies against citrullinated protein antigens (ACPAs), and the expression of PADI4 (mRNA) is higher in lung biopsies and leukocytes of subjects with severe COVID-19." (PMID 38524554, 2024).
HCMV infection (3 papers, 2021 to 2024). "Even though PADI2 and PADI4 are also marginally increased at the mRNA levels, their overexpression does not match the scale observed during HCMV infection of HFFs, where PADI3 expression remains basically unchanged." (PMID 39201398, 2024).
osteoarthritis (3 papers, 2013 to 2022). A noninflammatory degenerative joint disease occurring chiefly in older persons, characterized by degeneration of the articular cartilage, hypertrophy of bone at the margins and changes in the synovial membrane. "A western blot analysis was performed using synovial tissue from patients with RA (n = 7), osteoarthritis (OA, n = 7) and AS (n = 5) to determine the levels of expression of PADI2." (PMID 24339914, 2013). "Together with PADI4, the protein level of PADI2 was reported to be highly increased in RA synovial tissues compared with that in samples from patients with osteoarthritis and ankylosing spondylitis, and some SNPs of the PADI2 gene were shown to be significantly associated with the presence of RA." (PMID 35218410, 2022).
ovarian carcinoma (3 papers, 2020 to 2023). A malignant neoplasm originating from the surface ovarian epithelium. "For example, it has been reported that high expression of PADI2 was significantly associated with shorter overall survival and progression-free survival in patients with ovarian cancer." (PMID 37627159, 2023). "In this study, we determined that PADI2 was highly expressed in ovarian cancer samples and associated with poor prognosis." (PMID 32951601, 2020). "Our results are consistent with these studies, and PADI2 expression is significantly increased in ovarian cancer samples." (PMID 32951601, 2020). "We built two stable PADI2 low expression of ovarian cancer cell lines for subsequent experiment and verified the effect of PADI2 expression on the proliferation of A2780 and SKOV3 cells." (PMID 32951601, 2020). "The transcriptome sequencing results showed that PADI2 knockdown ovarian cancer cell line A2780-shPADI2 had a difference on the condition of |Log2 Fold change|> 2 and P-value < 0.05." (PMID 32951601, 2020). "The findings presented here suggest a novel therapeutic approach to the Olaparib resistance of ovarian cancer and PADI2 as a prognostic marker in advanced ovarian cancer enhances sensitivity of Olaparib to ovarian cancer." (PMID 32951601, 2020). "The purpose of this study was to investigate the biological role of PADI2 in ovarian cancer (OC) and the relative mechanism." (PMID 32951601, 2020). "Our results suggested that down-regulation of PADI2 combined with Olaparib played the role of anti-ovarian cancer by inhibiting EMT and STAT3 signaling pathway." (PMID 32951601, 2020). "A total of 1436 (for PFS) and 1657 (for OS) RNAseq data samples of ovarian cancer patients were split into 2 groups (high expression of PADI2 and low expression of PADI2) based on the expression level." (PMID 32951601, 2020). "PADI2 was upregulated in ovarian cancer samples and high PADI2 expression was correlated with poor outcome." (PMID 32951601, 2020). "However, the upstream of PADI2 and the role of PADI2 in olaparib against ovarian cancer cell metastasis remain to be further explored." (PMID 32951601, 2020). "Therefore, in this study we provided a novel manipulating strategy for Olaparib resistance to ovarian cancer by downregulation of PADI2." (PMID 32951601, 2020). "Therefore, we hypothesized that STAT3 phosphorylation might be related to the biological behavior of PADI2-mediated ovarian cancer cells." (PMID 32951601, 2020). "Therefore, we hypothesized that targeting PADI2 could affect the treatment of ovarian cancer with Olaparib through EMT." (PMID 32951601, 2020). "Downregulation of PADI2 in SKOV3 and A2780 ovarian cancer cells inhibited EMT-related markers and STAT3 phosphorylation." (PMID 32951601, 2020). "We further investigated the effect of PADI2 expression on the invasiveness of A2780 and SKOV3 ovarian cancer cells in vitro by transwell assays." (PMID 32951601, 2020). "After we constructed stable ovarian cancer cell lines A2780 and SKOV3 with low expression of PADI2, Downregulating PADI2 suppresses colony formation, proliferation, migration and invasion of A2780 and SKOV3 cells." (PMID 32951601, 2020). "Colony numbers of PADI2 knockdown A2780 and SKOV3 cells combined with Olaparib were significantly fewer than cells treated with Olaparib alone in A2780 and SKOV3 ovarian cancer cell lines.(P < 0.05)." (PMID 32951601, 2020). "Down-regulation of PADI2 enhanced olaparib's ability to inhibit invasion and migration of SKOV3 and A2780 ovarian cancer cells by inhibiting EMT." (PMID 32951601, 2020). "To confirm the role of PADI2 on anti-cancer effect, we silenced the expression of PADI2 and examined the modulation of PADI2 expression by Olaparib treatment combined with PADI2 knockdown in SKOV3 and A2780 ovarian cancer cells." (PMID 32951601, 2020).
ovarian carcinoma (continued). "We conducted MTT assay, cloning formation assay and EdU cell proliferation assay to detect the cell activity of PADI2 knockdown A2780 and SKOV3 ovarian cancer cells treated with Olaparib." (PMID 32951601, 2020). "Through the screen of differential genes and bioinformatics analysis, genes were closely related to ovarian cancer after downregulation of PADI2, such as STAT3 which was identified for further in-depth study on the occurrence and development of ovarian cancer." (PMID 32951601, 2020). "Overall, these results suggest that down-regulation of PADI2 enhanced Olaparib's ability to inhibit invasion and migration of A2780 and SKOV3 ovarian cancer cells." (PMID 32951601, 2020). "Collectively, It indicated that PADI2 knockdown could inhibit the invasiveness of A2780 and SKOV3 ovarian cancer cells." (PMID 32951601, 2020). "In summary, these results suggested that the level of PADI2 expression may affect the ability of SKOV3 and A2780 ovarian cancer cells to proliferate in vitro." (PMID 32951601, 2020). "PADI2 knockdown may be a potential anticancer approach for SKOV3 and A2780 ovarian cancer cell lines." (PMID 32951601, 2020). "It indicated that PADI2 knockdown could inhibit the invasiveness of A2780 and SKOV3 ovarian cancer cells and enhanced the ability of Olaparib to inhibit the invasiveness of ovarian cancer cells." (PMID 32951601, 2020).
primary open angle glaucoma (3 papers, 2010 to 2019). "Peptidyl arginine deiminase 2 (Gene name: PADI2) was found at significantly higher abundance in ONH than in RET samples and was reported to be elevated in human primary open-angle glaucoma (POAG) optic nerve." (PMID 31470587, 2019).
viral infection (3 papers, 2020 to 2026). "Interestingly, when Poly I:C was used as a synthetic analog of a dsRNA viral infection, there was a statistically significant and marked drop in PADI2 mRNA expression at 24 h and 48 h (p ≤ 0.05 and p ≤ 0.01, respectively)." (PMID 32117246, 2020).
atherosclerosis (2 papers, 2018 to 2023). A disease characterized by the build-up of fatty material and calcium deposition in the arterial wall resulting in partial or complete occlusion of the arterial lumen. "Several proteins downregulated in eWAT, such as PADI2, PSAP, NCK1, and NPM1, with proven pro-inflammatory properties that are normally secreted into the extracellular space, have been linked to the progression of atherosclerosis." (PMID 38017481, 2023).
endometrial tumor (2 papers, 2020 to 2021). "To confirm these findings, we compared PADI2 protein levels in clinical endometrial tumor tissues using immunohistochemistry." (PMID 33747724, 2021). "Herein, we demonstrated PADI2 protein expression in six primary endometrial tumors but lacked appropriate matched normal endometrium samples for comparison." (PMID 32248654, 2020).
hepatocellular carcinoma (2 papers, 2023). A malignant tumor that arises from hepatocytes. "In hepatocellular carcinoma, the downregulation of PADI2 inhibits EPO expression and promotes the proliferation and migration of hepatocellular carcinoma cells." (PMID 37020554, 2023).
Hypertension (2 papers, 2018 to 2023). The presence of chronic increased pressure in the systemic arterial system. "Moreover, our integrative analysis identified AQP4-AS1 and PADI2 as genes whose expression levels may contribute to the pleiotropy of complex traits involved in cardiovascular health and blood pressure regulation in response to an intervention targeting hypertension." (PMID 29710874, 2018).
Lyme disease (2 papers, 2022 to 2023). Lyme disease (named after the towns in the USA where the disease was first identified) is a bacterial infection caused by Borrelia burgdorferi. "PADI2 is associated with multiple sclerosis (MS) and posttreatment Lyme disease." (PMID 37020554, 2023). "Moreover, high PADI2 expression in the CNS leads to the exacerbation of MS and posttreatment Lyme disease (PTLD)." (PMID 37020554, 2023).
Obesity (2 papers, 2022). Accumulation of substantial excess body fat. "Again, 3 upregulated genes ADPRH, PADI2, and QKI are shared in T2D, obesity, and CVD." (PMID 36035865, 2022).
squamous cell carcinoma (2 papers, 2016 to 2020). A carcinoma arising from squamous epithelial cells. "They then found that the human squamous cell carcinoma cell line A431 with overexpressed PADI2 was more tumorigenic and contained elevated levels of markers for inflammation and epithelial-mesenchymal transition." (PMID 27478411, 2016). "Flag-PADI2 was stably overexpressed in A431 human squamous-cell carcinoma cell line." (PMID 32951601, 2020).
acute lung injury (1 paper, 2025). A condition of lung damage that is characterized by bilateral pulmonary infiltrates (pulmonary edema) rich in neutrophils, and in the absence of clinical heart failure. "Peptidyl arginine deiminase 2 (PAD2) plays a key role in regulating macrophage function in Pseudomonas aeruginosa‐induced acute lung injury (ALI)." (PMID 40087815, 2025).
age-related macular degeneration (1 paper, 2023). Age-related loss of vision in the central portion of the retina (macula), secondary to retinal degeneration. "In the retina, PADI2 and PADI4 are associated with age-related macular degeneration (AMD) in the human retina through their citrullination of proteins." (PMID 37020554, 2023).
biliary tract cancer (1 paper, 2023). "This study aimed to evaluate the prognostic value of peptidylarginine deiminase 2 (PADI2) protein expression in biliary tract cancer (BTC) patients." (PMID 37627159, 2023).
cleidocranial dysplasia (1 paper, 2023). "Our findings demonstrate that Padi2 deficiency leads to the loss of bone mass and results in a cleidocranial dysplasia (CCD) phenotype with delayed calvarial ossification and clavicular hypoplasia, due to impaired osteoblast differentiation." (PMID 37648716, 2023).
diabetic retinopathy (1 paper, 2018). "This region spans genes with plausible roles in the development of diabetic retinopathy, (e.g. PADI1, PADI2, PADI3, and PADI4, as well as genes known to be involved in kidney function (CLCNKA and CLCNKB)." (PMID 29444168, 2018).
ductal carcinoma in situ (1 paper, 2017). "Using a mouse model of ductal carcinoma in situ, we previously found that inhibition of peptidylarginine deiminase 2 (PAD2, aka PADI2) activity appears to maintain basement membrane integrity in xenograft tumors." (PMID 28549415, 2017).
glioma (1 paper, 2023). A benign or malignant brain and spinal cord tumor that arises from glial cells (astrocytes, oligodendrocytes, ependymal cells). "Gene expression analysis showed a non-significant increase in PADI2 mRNA levels in GBM versus normal brain tissues; however, IHC analysis showed lower protein levels in glioma than in normal brain tissues." (PMID 37762371, 2023).
lentivirus infection (1 paper, 2020). Virus diseases caused by the Lentivirus genus. "The statistical figure showed that PADI2 expression of lentivirus infection group was obviously lower than the control group." (PMID 32951601, 2020).
mycoplasma infection (1 paper, 2025). "The results revealed that as the multiplicity of infection increased, the luciferase signal also increased, indicating that mycoplasma infection can increase the expression of PADI2 through the SP3 transcription factor." (PMID 41146353, 2025). "Therefore, to investigate the function of PADI2 in infected macrophages, we designed and synthesized PADI2 overexpression plasmids and siRNAs and transfected them into cells 6 h before mycoplasma infection." (PMID 41146353, 2025).
Mycoplasma pneumonia (1 paper, 2025). "Targeting PADI2 to promote the polarization of M2 macrophages provides a promising approach for treating MO infection or preparing anti-Mycoplasma pneumonia gene-edited sheep." (PMID 41146353, 2025).
triple-negative breast carcinoma (1 paper, 2025). An invasive breast carcinoma which is negative for expression of estrogen receptor (ER), progesterone receptor (PR), and human epidermal growth factor receptor 2 (HER2). "Previously, our group established the enzyme protein arginine deiminase type-2 (PADI2), which catalyzes citrullination modification, is highly expressed in triple-negative breast cancer (TNBC), promoting antigenicity." (PMID 40573960, 2025).
ulcerative colitis (1 paper, 2017). An inflammatory bowel disease involving the mucosal surface of the large intestine and rectum. "In addition, a low level of PADI2 expression in the colon mucosa was also observed in patients with ulcerative colitis." (PMID 28229027, 2017).
uterine cancer (1 paper, 2020). Primary or metastatic malignant neoplasm involving the uterine corpus and/or the cervix. "However, the expression of PADI2 has been characterized in non‐uterine cancers." (PMID 32248654, 2020).
uterine carcinosarcoma (1 paper, 2020). A usually aggressive malignant neoplasm arising from the uterine corpus and less often the cervix. "Future determination of whether PADI2 expression correlates with FBXW7 mutation in uterine carcinosarcomas, which have somatic FBXW7 mutation rates of 11%‐39% (reviewed in Ref." (PMID 32248654, 2020).